IL6 (interleukin 6)
Diseases named in the same sentence as IL6 in open-access papers (continued):
Sharing a sentence is not in itself a finding about the gene and the disease.
tumor (continued). "IL6+CAFs probably modulate the tumor immune microenvironment and the activity of T-lymphocytes." (PMID 40227764, 2025). "Beyond general cytokine signaling, candidate pathways may include the IL-6/STAT3 axis and TGF-β signaling, both of which are implicated in tumor–stroma–osteoclast crosstalk in related cancer models." (PMID 41153834, 2025). "Furthermore, CAFs release a range of growth factors and cytokines, such as EGF, HGF, and IL-6, thereby enhancing the proliferation, survival, and invasive characteristics of tumor cells." (PMID 41394878, 2025). "Furthermore, CRP is an acute-phase protein influenced by IL-6 and TNF-α, linked to tumor aggressiveness and cachexia." (PMID 40786260, 2025). "Direct stimulation of tumor cells via IL-6 leads to increased cell proliferation and invasiveness." (PMID 40281902, 2025). "This phenomenon may be associated with postoperative regression of inflammation, decreased IL-6 levels and reduced tumor load." (PMID 40837560, 2025). "Notably, CAF-tumor cell cross-talk synergistically amplifies IL-6 production, establishing a complex paracrine network essential for chemoresistance and tumor progression." (PMID 40718440, 2025). "Furthermore, IL-6, acting as both a pro-inflammatory cytokine and anti-inflammatory myokine, influences tumor progression across cancer types." (PMID 40530335, 2025). "In the context of HL, where the tumor microenvironment is highly inflammatory, the presence of omega-3 may limit the activity of cytokines such as IL-6, TNF-α or IL-1β, which promote the proliferation of Reed–Sternberg cells and the progression of the disease." (PMID 41374067, 2025). "Additionally, MSLN increases the level of IL-6 secreted by tumor cells through the NF-κB signaling pathway." (PMID 41400642, 2025). "Additionally, ISG15 is associated with tumor angiogenesis, as its inhibition in certain cancers reduces the secretion of angiogenesis-related factors such as VEGF and IL-6, leading to suppressed tumor growth and invasiveness." (PMID 40208307, 2025). "It has been demonstrated that tumor cells release inflammatory cytokines (IL-6, IL-1, TNF-α), chemokines (CCL2, CCL5, CCL15, CCL26), and growth factors (TGFβ), which ultimately recruit BMDCs such as myeloid-derived suppressor cells (MDSCs) and create a favorable niche for tumor development." (PMID 41383620, 2025). "Notably, in TNBC, chromosomal instability (CIN)-driven STING signaling sustains tumor survival via IL-6/STAT3 activation." (PMID 41573551, 2025). "In turn, the reduction in soluble IL-6 and Gal-9 levels likely contributes to improved anti-tumor immunity by alleviating the pro-tumorigenic and immunosuppressive effects of IL-6 and by disrupting the interaction between Gal-9 and the immune checkpoint receptor TIM3 on T cells." (PMID 40108668, 2025). "These alterations are considered to be driven by changing circulating cytokines and chemokines profiles released by malignant cells such as TNFα, EGFR ligands, transforming growth factor‐beta (TGF‐β) and IL-6, contributing to local immune evasion and tumor progression." (PMID 38965182, 2025). "Interestingly, heat-stressed tumor-derived sEVs (HS-TEXs) can exert anti-tumor effects by converting immunosuppressive regulatory T cells (Tregs) into pro-inflammatory Th17 cells via IL-6 signaling." (PMID 40114183, 2025). "Additionally, we interrogated the dependency on the JAK1–STAT3 axis in maintaining this tumor-resistant cell identity based on evidence supporting the role of IL-6 signaling in promoting CSC treatment resistance." (PMID 40430044, 2025). "Thus, our results suggested that MCPIP1 reduced hybrid EMT and tumor stemness in PC cells by inhibiting the IL6/JAK2/STAT3 signaling axis." (PMID 40874680, 2025). "Interestingly, ADRr cells with higher MSN expression secreted significantly increased levels of IL-6 compared to naive tumor cell lines." (PMID 40696387, 2025).
tumor (continued). "Moreover, the inflammatory microenvironment induced by IL6 has been shown to influence the tumor’s ability to switch between “cold” and “hot” phenotypes." (PMID 40427188, 2025). "For example, trials of IL-6 or IL-6 receptor antibodies (clazakizumab and tocilizumab) in gastrointestinal cancers have shown reduced IL-6 levels, inhibited muscle loss, and improved albumin levels without accelerating tumor growth." (PMID 40869331, 2025). "To gain further insight into whether MCPIP1 intervenes in PC hybrid EMT and tumor stemness by regulating the IL6/JAK/STAT3 signaling pathway, we treated sh‐MCPIP1 PC cell lines with the IL6 inhibitor LMT‐28." (PMID 40874680, 2025). "TREM1 highly expressed in myeloid cells, maintains the tumor inflammatory microenvironment via the NF-κB/IL-6/STAT3 pathway; it may also directly activate pro-survival signals within tumor cells (e.g., PI3K-AKT)." (PMID 41415031, 2025). "Furthermore, IgG1 plasma cells were shown to promote the secretion of key inflammatory cytokines, including TNF-α, IL-6, and IL-10, which not only sustain immune responses but also contribute to immune evasion and tumor progression." (PMID 41357192, 2025). "Furthermore, a reduction in tumour-associated macrophages (TAMs), regulatory T lymphocytes (Tregs), vascular endothelial growth factor (VEGF), interleukin-4 (IL-4) and interleukin-6 (IL-6), which have immunosuppressive effects, was observed in BC." (PMID 41301715, 2025). "Through the downstream JAK‐STAT signaling pathway, METTL3 lactylation promotes the expression of immunosuppressive effector molecules such as interleukin (IL‐6, IL‐10, and inducible nitric oxide synthase), ultimately promoting tumor immune evasion and accelerating tumor growth and proliferation." (PMID 40443721, 2025). "Furthermore, sulforaphane suppresses the production of pro-inflammatory cytokines, such as IL-1β and IL-6, and has been demonstrated to potentiate the efficacy of immunotherapy by promoting an anti-tumor immune response." (PMID 40507159, 2025). "Finally, in the tumor microenvironment, IL-6 recruits immune cells like macrophages and neutrophils, releasing cytokines." (PMID 39980561, 2025). "Previous studies suggested that IκBζ target genes, such as IL1A, IL1B, or IL6, promote tumor cell proliferation, although it is unclear whether these cytokines are predominantly produced by the tumor cells or the surrounding TME19–21." (PMID 40562773, 2025). "This indicates that cisplatin not only acts via the known cytotoxic effect, but may induce a reduction in tumor-supporting proteins, like IL-6 and IDO1, by MSCs in the tumor microenvironment at subtoxic concentrations." (PMID 40699630, 2025). "In BC cells, the signaling pathways TNFα/NFκB and IL6/STAT3 are known to promote tumor progression via activation of key EMT-related transcription factors, such as Snail Family Transcriptional Repressor 1 (Snail1), Twist-related protein 1 (Twist1), and Zinc finger E-box binding homeobox 1 (ZEB1)." (PMID 40807456, 2025). "IL6 influences the activation of innate immune cells (such as macrophages and dendritic cells) and adaptive immune cells (such as T cells), enhancing the anti-tumor response and supporting the elimination of tumor cells." (PMID 40427188, 2025). "Conversely, IL‐6 drives apoptosis in tumor‐infiltrating T cells." (PMID 39811803, 2025). "Furthermore, exogenous IL-6 enhanced the survival of L-OHP-treated tumor cells, suggesting that IL-6 signaling is a key mechanism by which CAFs promote chemoresistance." (PMID 40718440, 2025). "Furthermore, there is evidence that IL-6 overexpression is particularly prominent in HPV-negative cancers but much less so in HPV-positive tumours." (PMID 39858048, 2025). "Conversely, IL-10 could also negatively regulate pro-inflammatory cytokines like IL-6 and IL-12/IL-23, maintain the homeostasis of anti-inflammatory Tregs, and suppress pro-inflammatory Th17 cells, which contribute to tumor growth." (PMID 39860614, 2025).
tumor (continued). "We hypothesize that IL-6/GP130/JAK/STAT3 pathway activation is comparable between tumor tissue and adjacent stromal tissue." (PMID 41397158, 2025). "First, IL-6 promotes tumor cell proliferation through STAT3 activation." (PMID 41244903, 2025). "These stromal cells can create a physical barrier to drug delivery and release pro-survival factors—such as interleukin-6 and stromal-derived factor-1—that modulate tumor cell plasticity and sustain a proangiogenic milieu counteracting VEGF-targeted inhibition." (PMID 41303595, 2025). "Furthermore, this study demonstrated that oral administration of the CB‐AKK combined bacteria significantly increased the levels of TNF‐α in both tumor tissues and serum, whereas simultaneously reducing the levels of IL‐6 and IL‐10." (PMID 40497373, 2025). "For example, IL-17 can promote tumour growth by activating the IL-6-Stat3 pathway." (PMID 40016789, 2025). "The IL-6 levels in CAF-derived CM were approximately 3.5-fold higher than in tumor cell-derived CM." (PMID 40718440, 2025). "Although interleukin (IL)-6 is considered immunosuppressive and tumor-promoting, emerging evidence suggests that it may support antitumor immunity." (PMID 39653766, 2025). "JAK/STAT3 hyperactivation in tumor cells may occur as a result of elevated IL-6 levels in the serum and/or in the tumor microenvironment or loss-of-function mutations affecting negative regulators of STAT3." (PMID 40428422, 2025). "In addition to IL-1, IL-6 drives tumor progression, and combined blockade of IL-6 and PD-L1 synergistically inhibits tumor growth in murine models." (PMID 40619414, 2025). "Notably, IL-1β can induce IL-6 production, a cytokine known to promote tumor progression via STAT3 activation." (PMID 41445736, 2025). "IL6 promotes tumor cell survival through PI3K/AKT and cyclin A1." (PMID 40041495, 2025). "These signals may be triggered by cytokines from the tumour microenvironment (for example, IL-6) or via IKK-mediated intracellular activation, linking extrinsic and intrinsic resistance mechanisms." (PMID 40806254, 2025). "For instance, key interleukins such as IL-6 and IL-8 play an important role in tumor progression." (PMID 41463272, 2025). "In addition to IL-6, CAFs can produce many other interleukins, including IL-10, IL-11, IL-22, IL-32, and inhibiting actions of these interleukins resulted in anti-tumour effects in some studies." (PMID 39780187, 2025). "According to the cytokine field theory, the tumor microenvironment increases proinflammatory cytokine levels, such as IL-6, which may, in turn, induce nearby cells to produce additional cytokines." (PMID 40143164, 2025). "As illustrated in the “Mast cells and macrophages” section, IL-6 secreted by macrophages can influence mast cells, thereby maybe producing additional effects that contribute to the tumor microenvironment." (PMID 39814702, 2025). "Blood-Based Biomarkers: Circulating tumour DNA (ctDNA) and inflammatory markers (e.g., IL-6) may complement imaging." (PMID 40722549, 2025). "Phytic acid reduces the expression of pro-inflammatory markers such as cyclooxygenase 2 (COX-2), inducible nitric oxide synthase (iNOS), interleukin-1 beta (IL-1β), interleukin-6 (IL-6), and interleukin-10 (IL-10), creating a less favorable environment for tumor growth." (PMID 39942108, 2025). "IL6 also drives tumor microenvironment immunosuppression through multiple mechanisms, including reduced expression of MHC-II, CD80/86, and IL-12 in dendritic cells, differentiation of dendritic cells to immunosuppressive M2 macrophages, and suppression of T-cell-mediated anti-tumor immunity." (PMID 41304808, 2025).
tumor (continued). "While tumor-derived interleukin-6, macrophage colony-stimulating factor, and prostaglandin E2 have been identified as factors inducing the transition from DC2s to ti-DC3s, a comprehensive unbiased profiling of the resulting changes in secretome and proteome has not been reported." (PMID 40789452, 2025). "However, cancer-derived cytokines such as TGF-β, IL-6, and IL-8 can attract and alter neutrophils, transforming them from an antitumor (N1) to a tumor-promoting (N2) phenotype." (PMID 40636453, 2025). "IL-6 is another key cytokine produced by CAFs that enhances tumor growth and immune evasion." (PMID 41179287, 2025). "First, tumor cells can secrete various cytokines (such as IL-6, IL-10, and TNF-α), and the changes in the expression of these cytokines not only affect the infiltration and activity of leukocytes but also promote alterations in the biochemical properties of surrounding fibroblasts." (PMID 40008000, 2025). "Interestingly, nicotinamide encapsulated in TEVs alters macrophage NAD + metabolism to activate IL-6/NF-κB signaling, thereby increasing the amount of pro-tumor macrophages in the TME." (PMID 40908470, 2025). "In our study, the pronounced antitumor effect of IL‐6 inhibition observed in vivo suggests that both tumor‐intrinsic and microenvironmental IL‐6 signaling may contribute to eribulin resistance." (PMID 41189442, 2025). "Furthermore, baseline serum IL-6 levels may influence the clinical response to this therapy, with lower IL-6 levels being associated with greater T-cell proliferation, cytokine production, and tumour-infiltrating T cells, leading to improved treatment outcomes." (PMID 40544399, 2025). "Importantly, while the hMSC feeding-layer primarily served as an IL-6 source, it is crucial to acknowledge the presence of sIL-6R within the tumor microenvironment." (PMID 38980514, 2025). "In the present study, we found that after BM of BC cells, Arg1+ microglia were significantly aggregated at the site of tumor metastasis, and the levels of cytokine IL6, chemokine CCL2, were significantly increased, suggesting an immunosuppressive microenvironment following BC-BM." (PMID 40444044, 2025). "Initially, its role as a pro-inflammatory cytokine serves to eliminate tumor antigens; however, as the cancer progresses, the polarization of naïve CD4+ T-helper cells towards pathogenic Th17 lineage releases IL-17 and also IL-6 cytokines that are important to advance tumor stage and development." (PMID 41376623, 2025). "This could be attributed to the persistent stimulation of T cells by tumor-associated inflammatory cytokines, such as IFN-γ and IL-6, which promote the proliferation of ADRB1+ T cells and drive them into an exhausted state." (PMID 40406147, 2025). "In addition, the HIF-1 signaling pathway shows the regulation of STAT3 after IL-6 stimulation, which shows the potential of BO in regulating immunity to achieve tumor treatment." (PMID 40076902, 2025). "Simultaneously, tumor cells may release cytokines, such as IL-6, which impede the formation of albumin in hepatocytes." (PMID 38169970, 2024). "In addition to their direct effects on tumor cells, SKs regulate pathologic inflammation from cytokines such as TNFα and IL-6." (PMID 38730731, 2024). "However, their tumour-killing abilities were compromised by the development of phagocytosis resistance in neighbouring tumour cells through the upregulation of CD47 in the highly inflammatory microenvironment (with elevated IL-6 levels)." (PMID 39025845, 2024). "A study has found a significant correlation between serum level of IL-6, serum cortisol and tumor-related symptoms, which may explain the predominant fatigue symptom presented in iMCD patient." (PMID 39702341, 2024). "Furthermore, a direct relationship between the levels of IL-6 and PD-L1 was found in the tumor tissues of patients with hepatocellular carcinoma." (PMID 38638430, 2024).
tumor (continued). "Surprisingly, the requirement for IL-6 remains intrinsic to cancer cells and transplantable via the corresponding tumor organoids, thereby highlighting opportunities to discover therapeutic vulnerabilities over and above the addiction to IL-6 signaling identified here." (PMID 39128004, 2024). "IL-6, a cytokine with various functions in cancer development and progression, is produced by different cell types including immune cells, fibroblasts, and tumor cells." (PMID 38338683, 2024). "In contrast, IL-6 knock-out mice presented a lower incidence of GC and reduced tumor size." (PMID 38422751, 2024). "A study found that cDC1 dysfunction could occur even in the early stages of pancreatic intraepithelial neoplasia and that tumor formation was accompanied by elevated IL-6 evoked cDC1 apoptosis in mice." (PMID 38167055, 2024). "In the present study, a positive correlation was found between IL-6 levels in plasma and the expression of CD71 on neutrophils, supporting our hypothesis that the expression of CD71 is associated with tumor progression in PDAC." (PMID 39256468, 2024). "In NSCLC-associated brain metastases, Tregs contribute to an immunosuppressive tumor microenvironment, often appearing in increased numbers alongside elevated levels of myeloid-derived suppressor cells (MDSCs), monocytes PD-L1 and IL-6 in the peripheral blood of affected patients." (PMID 38396722, 2024). "Importantly, blue LED reduced expression of cancer-associated fibroblast (CAF) activation markers like α-SMA and IL-6 in the tumor stroma." (PMID 39439950, 2024). "Interestingly, both in vivo and in vitro studies on fresh tumour samples confirmed that AM-MSC-derived IL-6 enhanced the levels of EMT factors and stem cell-related genes in epithelial cells from follicular AM (AM-EpiCs)." (PMID 39120301, 2024). "Indeed, while p62 normally acts as a suppressor of inflammation, its loss promotes the instauration of the CAF proinflammatory phenotype, associated with increased expressions of IL-6 and TGF-β, which in turn drives tumor progression." (PMID 39335188, 2024). "Transferring Micrococcus luteus in in vivo models hinders 4TI tumor growth, and this may be due to the microbiota upregulating M1-macrophage-related genes, which include, among others, the IL-6, IL-8, and IL-12 genes." (PMID 38256183, 2024). "CCK-8, EdU, and transwell assays showed that IL-6 could reverse the inhibitory effects of proliferation and migration of tumor cells owing to AQP3 knockdown in co-cultured model." (PMID 39060229, 2024). "Proinflammatory cytokines IL-1, IL-6, TNFα, and IL-17 play an important role in the regulation of inflammation and are capable of stimulating proliferative and antiapoptotic signals in epithelial and tumor cells or inducing angiogenesis." (PMID 39637122, 2024). "Additional studies are warranted to delve deeper into the specific mechanisms through which TGF-β3, TSLP, and possibly other tumor-derived factors may contribute to myeloid cell education and elevated IL-6 and OSM expression." (PMID 38236642, 2024). "In addition, IL-6 expression in the tumor tissues correlated positively with SPZ1 expression (R2 =0.6719)." (PMID 39440046, 2024). "In addition, previous studies have reported that TA-MSC secreted bFGF, PDGF, and SDF1 to recruit more naive MSC into the TME; and IL6 to enhance tumor cell growth." (PMID 38515582, 2024). "These successful experiments supported the idea that IL-6/IL-6R neutralization may by exploited to reactivate the T cell compartment and counteract tumor development." (PMID 39281678, 2024). "This could have significant clinical implications as the use of TIS as a clinical entity remains controversial, largely due to the tumour-promoting properties of SASP cytokines such as IL-6 in certain contexts." (PMID 38255248, 2024). "IL-6 in turn activates pathways that stimulate cell proliferation, differentiation, metastasis, and upregulation of antiapoptotic and angiogenic proteins in tumor cells." (PMID 39184804, 2024).